WT1 (WT1 transcription factor)
Diseases named in the same sentence as WT1 in open-access papers (continued):
Sharing a sentence is not in itself a finding about the gene and the disease.
Wilms tumor (continued). "Importantly, Wilm's tumor with WT1 mutation tends to occur early with a median age of 15–19 months vs. a median age of 36 months in children without a pathogenic WT1 variant." (PMID 35498778, 2022). "Membranoproliferative glomerulonephritis is not commonly associated with disorders of sex development but has been recently identified as a WT1-associated nephropathy, but usually in cases of exonic mutations in either isolated Wilms tumor or Denys-Drash syndrome." (PMID 35211794, 2022). "WT1 mutations may lead to nephroblastoma, glomerular sclerosis, gonadal dysgenesis, congenital diaphragmatic hernia, and cardiac disease." (PMID 34205452, 2021). "WT1 is a transcription factor, mutated it has been associated with the development of Wilms’ Tumor." (PMID 34301805, 2021). "Frasier syndrome is caused by mutations in the splice donor site at intron 9 of the Wilms' tumor WT1 gene; these mutations result in an imbalanced ratio of WT1 protein isoforms and affect the development of the urogenital tract, podocyte function, and tumor suppression." (PMID 34438508, 2021). "WT1 was originally reported to be a causative gene in the genesis of nephroblastoma." (PMID 34205452, 2021). "For instance, homozygous loss of the Wilms tumor driver gene Wt1 was shown to be embryonically lethal in mice, whereas a specific Wt1 ablation at E11.5 in a small fraction of nephron progenitor cells resulted in Wilms tumor formation." (PMID 33718380, 2021). "However, later it became clear that mutations of WT1 only occur in a low frequency in nephroblastoma and that most nephroblastomas express high levels of WT1." (PMID 34299295, 2021). "WT1 was originally identified as a tumor suppressor based on its mutational inactivation in nephroblastoma, but later studies provided evidence that WT1 might act as an oncogene." (PMID 32375405, 2020). "This subtype of Wilms tumor often carries WT1 mutations and most also harbor CTNNB1 mutations." (PMID 33379206, 2020). "WT1 gene mutations result in a WT1 protein with a decreased ability to bind to DNA, leading to uncontrolled growth, and cell division in the kidney which permits the development of Wilms tumor." (PMID 32056389, 2020). "Moreover, mutations in typical Wilms tumour genes were identified, such as WT1, DIS3L2, WTX, CTNNB1 and the miRNA-processing genes DROSHA, DGCR8 and DICER1." (PMID 32161258, 2020). "Originally described in association with Wilms tumor (a kidney tumor), Wilms Tumor 1 (WT1), which plays a key role in urogenital development, is now more generally described as an oncogene in some cancer entities including leukemias and also as tumor suppressor in others." (PMID 32408494, 2020). "For example, patients with Denys-Drash Syndrome, which is a rare disorder characterized by abnormal kidney function believed to be due to a mutation in the WT1 gene, have an estimated 90 percent chance of developing a rare form of kidney cancer known as Wilms tumor." (PMID 31044086, 2019). "Heterozygous intragenic, dominant-negative mutations in WT1 have been identified in several overlapping developmental disorders characterised by Wilms tumour, genital malformations, male-to-female sex reversal, nephropathy, diaphragmatic hernia and gonadoblastoma." (PMID 30242502, 2019). "Nephrogenic rests (precursors to malignant Wilms' tumors) formed as a consequence of mono-allelic inactivation transformed into the eponymous renal malignancy upon secondary WT1 allele inactivation, a classic example of Knudson's two hit hypothesis." (PMID 29623275, 2018). "Here, we analyzed whether induction of muscle cell differentiation is a common feature of chemotherapy‐treated Wilms tumors with different WT1 mutations." (PMID 29542868, 2018). "These animals were generated by breeding transgenic mice expressing Cre recombinase under the control of the Wilms Tumor one locus (Wt1-Cre) to animals carrying the floxed Zfp423 alleles (Zfp423loxP/loxP) (Zfp423loxP/loxP; Wt1-Cre animals, herein ‘Vis-KO’ mice)." (PMID 28722653, 2017).
Wilms tumor (continued). "However, only a fraction of Wilms' tumours have WT1 inactivating mutations, and in other cases WT1 rather shows overexpression." (PMID 29152069, 2017). "WT1 is a transcription factor which regulates the epithelial-mesenchymal balance during embryonic development and, if mutated, can lead to the formation of Wilms’ tumour, the most common paediatric kidney cancer." (PMID 28345629, 2017). "The origin/fate of Wilms tumors with WT1 mutations is currently poorly defined." (PMID 27213811, 2016). "Interestingly, hnRNP-U/SAF-A was also found to be associated with WT1 (Wilms tumor 1) protein and suggested to be a potential Wilms tumor gene." (PMID 27303920, 2016). "In addition, WT1 mutations affecting the zinc finger (ZnF) domains are implicated in Wilms tumor and acute myeloid leukemia (AML)." (PMID 25807502, 2015). "The Wilms’ tumor gene WT1 consists of 10 exons and encodes a zinc finger transcription factor." (PMID 26090994, 2015). "Wilms' tumor 1 gene, wt-1, is homozygously mutated in a subset of Wilms' tumors." (PMID 24288526, 2013). "The Wilms’ tumor gene (WT1) which is located at 11p13q, encodes a 52–54 kDa protein that containing four zinc finger transcriptional factors and was first identified as a tumor suppressor gene in nephroblastoma or Wilms’ tumor, a pediatric kidney cancer." (PMID 23936312, 2013). "The biological explanation for this association is obscure, but it may indicate that WT1 mutations are associated with a more rapid progression to Wilms tumor than other molecular abnormalities." (PMID 22470196, 2012). "For example, WT1 encoded by the Wilms' tumor gene inhibits replication by binding to SV40 origin." (PMID 22545052, 2012). "The effect of Wt1 loss on bone and fat turnover is interesting in the context of Wilms' tumours." (PMID 22216009, 2011). "Mutation of the Wilms tumour gene, WT1, in humans may lead to the eponymous paediatric kidney cancer, glomerulosclerosis of the kidney and gonadal dysgenesis, which can manifest as male to female sex reversal." (PMID 22216009, 2011). "Most strikingly, many of the newly proposed targets of WT1 are significantly enriched in chromosomal locations previously known to be associated with Wilms' tumor, indicating that the new targets could be relevant to this disease." (PMID 18564415, 2008). "However, (i) I found in PubMed that HRAS and MUCDHL have been already considered as the genes which are strongly associated with WT1 functions and Wilms tumor phenotype." (PMID 18564415, 2008). "In Wilms tumor, different point mutations have been described in the WT1 locus, suggesting that WT1 altered protein may be directly involved in tumor formation." (PMID 17137506, 2006). "In Wilms' tumours, mutation of the Wilms tumour 1 (WT1) gene at the WT1 locus has been reported, and the WT2 locus, comprising the two independent imprinted domains IGF2/H19 and KIP2/LIT1, can undergo maternal deletion or alterations associated with imprinting." (PMID 16909133, 2006). "However, WT1 aberrations, such as deletions and point mutations, are observed in only approximately 10–20% of Wilms' tumours." (PMID 16909133, 2006). "Patients with WT1 mutant Wilms tumor may harbor germline mutations in this gene." (PMID 33379206, 2020). "For example, upon identification of a mutation within the WT1 gene, a clinician should investigate the gender genotype of females to exclude an XY genotype with pseudohermaphroditism, and the patient should be screened for development of a Wilms tumor or gonadoblastoma." (PMID 28752288, 2018). "In one child with WAGR syndrome, caused by deletion of not only WT1 but also neighbouring genes including PAX6, the Wilms tumour harboured gain of chromosome 1." (PMID 39665570, 2025). "The limitation of this study is that the patient died at the age of 1.5 months before reaching the average onset age of Wilms tumor in patients with WT1-related nephropathy of DDS subtype." (PMID 41450889, 2025).
Wilms tumor (continued). "Other genes related with sepsis are the programmed cell death protein 1 (PD-1) and programmed death ligand 1 (PD-L1), and The Wt1 (Wilms tumour) gene." (PMID 41013722, 2025). "It confirmed that WT1 mutations were present in a significant subset of patients, some of whom also developed bilateral Wilms tumors, highlighting the dual role of WT1 in gonadal and renal development." (PMID 41220431, 2025). "An example is Wilms’ tumour, WT1, a transcription factor that has an important role in developmental processes and cell survival." (PMID 40276932, 2025). "The top three most frequently occurring keywords were “Expression” (469 occurrences), “Wilms tumor” (304 occurrences) and “WT1” (282 occurrences)." (PMID 40715920, 2025). "Alterations in the WT1 gene are linked to a wide array of illnesses, including WAGR syndrome (marked by Wilms tumor, aniridia, genitourinary malformations, and intellectual disability), Denys–Drash syndrome (DDS), Frasier syndrome, and Meacham syndrome." (PMID 40426774, 2025). "The BS1 values in this study ranged from 0.000003 for WT1-related Wilms tumor to 0.0058 for ATP7B-related Wilson disease." (PMID 41000626, 2025). "In keyword co-occurrence analysis, the frequent research hotspots in the field of WT targeted therapy were “Expression”, “Wilms tumor” and “WT1”." (PMID 40715920, 2025). "WT1, which is positive in more than 90% of all nephroblastomas, especially those with a blastemal and proliferative epithelial component, is one of the most helpful markers." (PMID 40177273, 2025). "Wilms tumors usually strongly express WT1 and fail to express membranous CD99, FLI-1, or nuclear NKX2.2." (PMID 40978053, 2025). "Wilms tumours are often positive for keratin, vimentin, desmin, actin, and WT1, which distinguishes this type of tumour from other malignancies." (PMID 40177273, 2025). "AMER1/WTX binds to WT1, a zinc-finger transcription factor and also a Wilms tumor suppressor, and enhances WT1-mediated transcription of target genes." (PMID 39941813, 2025). "The Wt1(Wilms tumour) gene instead, is related with post-transcriptional and post-translational activity, and it also acts in the development of organs or tissues and in maintaining their homeostasis." (PMID 41013722, 2025). "Several published studies have shown that WT1 is oncogenic in Wilms tumors and hematological malignancies." (PMID 40493404, 2025). "WT1 was first identified as an oncosuppressor in the Wilms’ tumors, but subsequent studies demonstrated its oncogenic function in several solid and hematologic malignancies." (PMID 40399259, 2025). "Nephroblastomas are generally positive for keratin, vimentin, desmin, actin, and WT1, allowing this form of tumour to be distinguished from other unusual entities." (PMID 40177273, 2025). "WAGR syndrome is a syndrome caused by a microdeletion of the short arm 13 region of chromosome 11, which results in Wilms’ tumor following the deletion of the WT1 gene in the same region." (PMID 39997047, 2025). "WT1 was first known as a tumor suppressor gene in Wilms tumor, regulating the differentiation of renal and gonadal cells." (PMID 38944027, 2025). "As a result, all the 15 DSRCTs (100%) demonstrated strong WT1 (C-19) nuclear immunoreactivity, while 71% of the Wilms tumors showed WT1 positivity nuclei, and only 2 out of 17 rhabdomyosarcomas demonstrated rare and focal nuclear positivity for WT1." (PMID 39682287, 2024). "Through interactions with WT1, a key transcription factor implicated in Wilms’ tumour, BASP1 and WT1 promote tumour-suppressing gene expression, induce cell differentiation, and upregulate genes for neurite outgrowth." (PMID 38398114, 2024).
Wilms tumor (continued). "Some of the most common genetic alterations of pediatric Wilms tumor include IGF2 overexpression, WT1, and CTNNB1 mutations." (PMID 39234402, 2024). "The histological differential diagnosis of CMN includes metanephric stromal tumor (CD34 positive), stromal type Wilms tumor (WT-1 positive), and inflammatory myofibroblastic tumor (ALK-positive), all of which were negative in our case." (PMID 39493139, 2024). "WTAP was originally named because of its association with the tumor suppressor gene Wilms tumor 1 (WT1), mutations in which cause Wilms tumor, a rare form of kidney cancer that occurs almost exclusively in children." (PMID 39238441, 2024). "The same group of investigators studying sporadic Wilms tumors then found the frequencies of WT1 abnormalities to be similar between their Japanese cohort and Caucasian populations." (PMID 39272909, 2024). "The WT1 gene, which was first discovered in Wilms' tumor, produces a transcription factor that is essential for regular cellular activity, but it is overexpressed in a number of cancers, such as leukemia, ovarian, and pancreatic cancers." (PMID 38665761, 2024). "The WT1 gene overexpression in Wilms tumors targets insulin-like growth factor II, which aids in aberrant cell proliferation." (PMID 38352075, 2024). "Known molecular drivers of Wilms tumor commonly involve disruptions to key transcription factors (TFs) (e.g., WT1, SIX2) and signaling proteins (e.g., IGF2, WTX, β-catenin) crucial for nephrogenesis." (PMID 39009564, 2024). "Initially, the WT1 gene was proposed as a specific proto-oncogene of metanephric nephroblastoma, i.e., Wilms’ tumor, the most frequent pediatric RCC subtype." (PMID 38929778, 2024). "Immunotherapy, mainly through WT1-targeting cancer vaccines, has emerged as a promising advancement in managing Wilms tumor (WT)." (PMID 39062028, 2024). "The aim of this work was to explore the possible developmental origin of the WT1 mutant subgroup of Wilms tumors by comparing the transcriptomes of the established Wilms tumor cell lines with those identified in early human kidney development." (PMID 36689432, 2023). "WT1, on the other hand, is important at several stages of nephrogenesis and nuclear expression is frequently recognised in Wilms tumour cells." (PMID 37186071, 2023). "In order to get a better insight into the timing of WT1 mutant Wilms tumor development, we compared the gene expression profiles of nine established WT1 mutant Wilms tumor cell lines with published data from different kidney cell types during development." (PMID 36689432, 2023). "In Wilms tumor, the characteristic WT1 expression was observed, while NKX2.2's absence reaffirmed its irrelevance in this context." (PMID 38234938, 2023). "Deletions of the WT1 locus result in the formation of Wilms tumors, the most common renal tumor in children." (PMID 38093359, 2023). "Wilms’ tumor 1 (WT1) is a tumor suppressor gene identified in Wilms tumors that participates in the embryogenesis of many organs by regulating multiple target genes and signaling pathways." (PMID 36832092, 2023). "Other risk factors for kidney disease and ESRD include WT1‐associated syndromes such as Denys–Drash (DDS), WAGR (Wilms tumor, aniridia, genitourinary malformations, and mental retardation/impaired cognitive function), and bilateral Wilms tumor." (PMID 35841204, 2023). "Wilms’ tumor gene WT1 up-regulation increases the mRNA of CYP 17a1 and decreases progesterone secretion, likely by the inhibition of CYP 11a1 and 3β-Hsd." (PMID 37110661, 2023). "The simultaneous expression of these genes indicates that WT1 mutant Wilms tumors develop at an early step of kidney differentiation with a faulty induction of differentiation in all lineages." (PMID 36689432, 2023). "Out of 27 Wilms tumor cases, 100% displayed positivity with WT1, 22.22% with PAX8, and 7.40% with BCL2." (PMID 37908610, 2023).
Wilms tumor (continued). "Although originally considered as a tumour suppressor in Wilms’ tumour, subsequent studies in various types of human malignancies indicated that WT1 is overexpressed and possesses oncogenic activities via distinct mechanisms." (PMID 37667197, 2023). "Wilms’ tumour gene 1 (WT1) was first identified as a tumour suppressor in Wilms’ tumour, a childhood kidney neoplasm." (PMID 37667197, 2023). "For instance, among Wilms' tumor cases,an overwhelming 100% displayed positivity with WT1, while 22.22% and 7.40% exhibited positivity with PAX8 and BCL2, respectively, aligning with findings fromearlier studies." (PMID 37908610, 2023). "Over 30 mutations or missense variants of the WT1 protein have been analyzed, reported, and correlated with phenotypes that include proteinuria, ESKD, genital anomalies, and Wilm's tumor." (PMID 35498778, 2022). "The present study explored the association between WT1 and TERT because WT1 is mutated in approximately 20% of Wilms tumor specimens and has been previously shown to interact with the TERT promoter." (PMID 35406427, 2022). "On the other hand, although WT1 behaves as a tumor suppressor gene in Wilms’ tumors, increasing data suggest a role for WT1 as an oncogene in both leukemia and solid tumors." (PMID 35465313, 2022). "The genomic studies of familial cases of Wilms tumor have allowed the identification of germline variants in the DICER1, WT1 (WT1 Transcription Factor), CHEK2 (Checkpoint Kinase 2), and PALB2 (Partner And Localizer Of BRCA2) genes." (PMID 36295546, 2022). "The most sensitive IHC markers for mesothelioma include calretinin, cytokeratin 5/6, and Wilms’ tumor (WT-1)." (PMID 36171577, 2022). "Another key transcription factor in the development of the kidney is WT1 transcription factor (WT1), which serves as a tumor-suppressor gene in Wilms tumors." (PMID 35626336, 2022). "In fact, beyond nephroblastomas, the currently available data on the topic of evaluating WT1 expression by using IHC in aRCCs are scarce and inconsistent." (PMID 35453662, 2022). "This study sought to understand the mechanism of increased TERT expression by determining the association between TERT and WT1 and N-MYC, two proteins important in Wilms tumor pathogenesis that have been shown to regulate TERT expression." (PMID 35406427, 2022). "The rest of the available data on WT1 protein expression in aRCCs come from comparative studies with other types of neoplasms, mainly pleural mesothelioma and nephroblastoma, known for consistent WT1 nuclear staining, and the contradictions are rampant." (PMID 35453662, 2022). "WT1 was initially identified as a suppressor of renal childhood cancer (Wilms tumour, nephroblastoma)." (PMID 34846543, 2022). "The deletion of chromosome 11p13 involving the WT1 and PAX6 genes has been shown to cause WAGR syndrome (OMIM #194072), a rare genetic disorder that features Wilms’ tumor, aniridia, genitourinary anomalies, as well as mental retardation." (PMID 36011342, 2022). "WT1 (The Wilms tumor gene): WT1 was first identified as the gene responsible for the development of the Wilms kidney tumor that primarily affects children." (PMID 35626018, 2022). "In contrast, overexpression of WT1 has been observed in nephroblastoma, breast and colon cancer or acute myeloid leukemia." (PMID 35610319, 2022). "The detection of chromosomal abnormalities on chromosome 11p in cases of WAGR syndrome eventually led to the localization and identification in 1991 of the WT1 gene, a gene involved in the pathogenesis of Wilms tumor." (PMID 35205416, 2022). "wt1 was identified by positional cloning as a responsible gene for Wilms’ tumor, a pediatric kidney tumor that affects 1 in 10,000 children." (PMID 36412640, 2022).